PSEN1 (presenilin 1)
Diseases named in the same sentence as PSEN1 in open-access papers (continued):
Sharing a sentence is not in itself a finding about the gene and the disease.
acne inversa (5 papers, 2017 to 2025). "One PSEN1 mutation, Pro242fs was linked to hidradenitis suppurativa (HS) or acne inversa, which is a skin disease." (PMID 37176125, 2023). "The role of gamma secretase in acne inversa has been investigated, including PSEN1, presenilin enhancer 2 (PEN2) and nicastrin (NCT)." (PMID 37176125, 2023). "Besides AD, truncation mutations in PSEN1 and PSEN2 were associated with a wide range of disease phenotypes, such as FTD, acne inversa, and acute encephalopathy." (PMID 39596030, 2024). "Haploinsufficiency was proven in the case of PSEN1 Pro242Leufs, which resulted in acne inversa." (PMID 39596030, 2024). "Additionally, two PSEN1 mutations presented non-neurodegenerative phenotypes, including acne inversa or dilated cardiomyopathy." (PMID 37176125, 2023). "Interestingly, PSEN1 Pro242fs and Asp333Gly could impact acne inversa and DCM, respectively." (PMID 37176125, 2023). "Interestingly, PSEN1 mutations may also impact non-neurodegenerative phenotypes, including PSEN1 Pro242fs, which could cause acne inversa, while Asp333Gly was reported in a family with dilated cardiomyopathy." (PMID 37176125, 2023). "Reduced expressions of mutant PSEN1 and NCT appeared in acne inversa patients." (PMID 37176125, 2023). "In addition to AD, PSEN1 or PSEN2 haploinsufficiency may be related to other phenotypes, such as acne inversa, retinitis pigmentosa, or FTD." (PMID 39596030, 2024).
Anxiety (5 papers, 2020 to 2024). Intense feelings of nervousness, tension, or panic often arise in response to interpersonal stresses. "The behavioural experiments indicate that APP/PSEN1-Tg mice showed early anxiety-like and depressive-like traits, symptoms which would be expected to be associated with dysfunction of the amygdaloid, hippocampal and PFC circuitries." (PMID 33795014, 2021). "We tested vision, anxiety and spatial orientation performance at four age levels of 4, 6, 9, and 12 months across male and female TgF-344 AD rats carrying human genes for presenilin-1 and amyloid precursor protein." (PMID 34679365, 2021).
Atrophy (5 papers, 2015 to 2024). Any weakening or degeneration, especially through lack of use. "In contrast, paroxetine significantly exacerbated the gliosis (p = 0.020) and also led to hippocampal atrophy (p = 0.010) in the APP/PSEN1 mice." (PMID 38259283, 2023). "The most common neuroimaging finding was atrophy, which was observed in >60% of all subgroups, and 90% of the PSEN1+/APOE4+ patients presented with atrophy with or without vascular lesions." (PMID 37958671, 2023).
B vitamin deficiency (5 papers, 2017 to 2023). "On the contrary, despite the existence of limited contradicting studies regarding PSEN1 gene, in vitro and in vivo studies have associated B-vitamin deficiency with enhanced PSEN1 expression due to hypomethylation of its promoter." (PMID 35053330, 2022). "Exploiting a nutritional B-vitamin deficiency paradigm, we have previously shown that PSEN1 and BACE1 activity is modulated by one-carbon metabolism, leading to increased amyloid production." (PMID 28973985, 2017). "Indeed, we demonstrated that the methylation impairment caused by B vitamin deficiency resulted in the promoter hypo-methylation of PSEN1 (Presenilin 1), a gene encoding for the peptide constituting the active site of the multiprotein γ-secretase complex." (PMID 37511434, 2023). "Bisulfite modification and genomic sequencing to evaluate the methylation status of PSEN1 revealed that vitamin B deficiency induced hypomethylation of specific CpG moieties in the 5′-flanking region and that PSEN1 promoter methylation status is correlated with gene expression." (PMID 35053277, 2022).
cardiomyopathy (5 papers, 2017 to 2023). A disease of the heart muscle or myocardium proper. "For the remaining MYH7 HCM samples, variants in the following other cardiomyopathy genes were also found: DSP, MHY6, NEBL, PSEN1, RBM20, and TTN." (PMID 32344918, 2020). "For example, mutation in presenilin 1 (PSEN1) and presenilin 2 (PSEN2) are associated with cardiomyopathies." (PMID 31671574, 2019).
Cerebral ischemia (5 papers, 2011 to 2022). Restriction of arterial blood supply to the brain associated with insufficient oxygenation to support the metabolic requirements of the tissue. "Thirty days after the termination of cerebral ischemia, the expression of presenilin 1 gene increased above the control value and presenilin 2 decreased below the control." (PMID 30545070, 2018). "Seven days after cerebral ischemia, gene expression of presenilin 1 was reduced, and presenilin 2 was significantly elevated." (PMID 30545070, 2018). "In the hippocampal CA1 region, the expression of the presenilin 1 and 2 gene was above the control value two and seven days after brain ischemia." (PMID 30545070, 2018). "In addition, the opposite trend in the expression of presenilin 1 and 2 indicates that two presenilins can play different roles under rat brain ischemia." (PMID 31713815, 2020). "Evidence therefore suggests that various forms of dysregulation of the APP, BACE1 and PSEN1 and PSEN2 genes are associated with individual neuronal cell responses in the CA1 and CA3 areas of the hippocampus and temporal cortex with reversible cerebral ischemia." (PMID 35741821, 2022).
epilepsy (5 papers, 2020 to 2022). A brain disorder characterized by episodes of abnormally increased neuronal discharge resulting in transient episodes of sensory or motor neurological dysfunction, or psychic dysfunction. "Although epilepsy may be associated with different PSEN1 mutations, this case presented an atypical early-onset epilepsy." (PMID 36142879, 2022). "The presenilin 1 gene (PSEN1) mutations are demonstrated to be associated with AD and epilepsy." (PMID 34697589, 2021). "This hypothesis is supported by the fact that mutations in Dlg3, Psen1, Dnm1, and Ppp3ca have been found in epilepsy patients." (PMID 32033586, 2020). "The prevalence of epilepsy was 60% in patients with APP duplication and 45% for those with PSEN1 mutation." (PMID 34121170, 2021). "Among patients with AD, the burden of epilepsy development is significantly higher for those with the inherited form of AD, which is associated with autosomal-dominant mutation of specific genes encoding the APP protein, PSEN1 and PSEN2." (PMID 34121170, 2021). "We speculated that the upregulated genes Grin1 and Prkce, Actin2, Mapk1, Psen1, and Nsf might contribute to the comorbidity of autism with epilepsy and abnormal learning and memory." (PMID 32033586, 2020). "We hypothesize that the upregulation of NMDAR interactors, such as Dlg3, Myh10, Ppp3a, Psen1, and Dnm1, may contribute to the anti-epilepsy phenotype by keeping the activity of NMDARs in control." (PMID 32033586, 2020).
hyperhomocysteinemia (5 papers, 2011 to 2025). A serious metabolic condition caused by mutations in the MTHFR gene, medications, or nutritional deficiency. "Liraglutide reduces APP expression and phosphorylation, BACE1 and PSEN1, and increases α-secretase in hyperhomocysteinemia and AlCl3-induced AD." (PMID 41146261, 2025). "Deficiencies in folate, vitamin B12, and B6 in AD mouse models (Tg2576 and TgCRND8) increase Aβ deposition, likely through hyperhomocysteinemia affecting γ-secretase activity and presenilin-1 (Psen1) promoter methylation." (PMID 40717068, 2025). "PSEN1 5′-flanking region has a site-specific (only few CpG moieties) methylation pattern that could change in response to metabolic stimuli, vitB deficiency (resulting in hyperhomocysteinemia in mice) causes PSEN1 overexpression through DNA demethylation which can be prevented by SAM." (PMID 35813941, 2022).
ovarian carcinoma (5 papers, 2018 to 2022). A malignant neoplasm originating from the surface ovarian epithelium. "Moreover, some genetic variants are shared, but there are also certain population specificities, such as WNT4, ESR2, and PSEN1 gene polymorphisms, which have been reported to be involved in ovarian cancer in Chinese individuals." (PMID 36685881, 2022). "For this reason, the expression levels of miR-27-3p and PSEN-1 in ovarian cancer tissue samples will be further tested in the future, and whether miR-27-3p can upregulate ovarian cancer cells’ sensitivity to Olparib." (PMID 34169001, 2021). "Therefore, in this study, we hypothesized that CAFs were involved in immunosuppression in ovarian cancer via upregulation of presenilin 1 (PS1)." (PMID 32587587, 2020). "Highly expressed presenilin 1 (PS1) in CAFs attenuates the proliferation and infiltration of CD8+ T cells and dendritic cells via the WNT/β-catenin pathway in ovarian cancer." (PMID 35681617, 2022).
schizophrenia (5 papers, 2007 to 2020). A major psychotic disorder characterized by abnormalities in the perception or expression of reality. "TRAF6, PRKACA and ACTN1 are all connected to both SRC and PSEN1 and therefore it might be useful to further investigate their interactions in order to better understand the mechanisms that could be involved in Schizophrenia." (PMID 32735660, 2020). "In addition, in the neurotrophin signaling pathway, it has been reported that the expression of gene PSEN1 is significantly decreased in schizophrenia and bipolar patient groups, supporting PSEN1 as a potential biomarker for both diseases." (PMID 31530853, 2019).
bladder cancer (4 papers, 2021). "Moreover, Kaplan–Meier survival analysis showed that higher levels of Presenilin 1 and Nicastrin expression (p < 0.05) were associated with significantly poorer overall survival in patients with bladder cancer." (PMID 34059639, 2021). "PSEN1 is a direct target gene of miR-193a, and PSEN1 promoted cell apoptosis and enhanced the sensitization to a drug in bladder cancer." (PMID 34335753, 2021). "More importantly, however, PSEN1 was negatively correlated with chemotherapy resistance of bladder cancer cells." (PMID 34568005, 2021). "Numerous studies theorized that PSEN1 repression can hasten radiotherapy and chemotherapy resistance of varying cancers including esophageal cancer and bladder cancer." (PMID 35096015, 2021). "The data suggest that CPX downregulates the Notch pathway in bladder cancer cells by inhibiting the γ-secretase complex proteins Presenilin 1 and Nicastrin." (PMID 34059639, 2021). "On the other hand, we have observed that CPX binds γ-secretase complex proteins Presenilin 1 and Nicastrin to inhibit Notch signaling, suggesting that CPX targets the γ-secretase complex in bladder cancer cells." (PMID 34059639, 2021). "Dysregulation of presenilin-1 (PSEN1), the dominant component of γ-secretase complex, is a key regulator in tumorigenesis and progression, participating in biological and pathological processes of colorectal cancer, bladder cancer, liver cancer, and so on." (PMID 35096015, 2021).
dilated cardiomyopathy (4 papers, 2017 to 2023). Cardiomyopathy which is characterized by dilation and contractile dysfunction of the left and right ventricles. "Dilated cardiomyopathy (DCM) was related to PSEN1 Asp333Gly mutation." (PMID 37176125, 2023). "Moreover, these gain of function mutations to presenilin 1 are shown to enhance the amplitude of Ca2+ release through RyR, and have also been associated with the development of dilated cardiomyopathy and heart failure." (PMID 28384221, 2017). "Mutations of presenilin 1 (PSEN1) and presenilin 2 (PSEN2) genes associated with familial AD have been found in patients with dilated cardiomyopathy." (PMID 35019033, 2022).
Huntington disease (4 papers, 2013 to 2025). Huntington disease (HD) is a rare neurodegenerative disorder of the central nervous system characterized by unwanted choreatic movements, behavioral and psychiatric disturbances and dementia. "Upregulation of MEG3, TRIM4, and TCEAL5 were reported in different models of Huntington’s disease with an intracellular aggregation of mutant HTT, suggesting a link between PSEN1 ΔE9 and mutant HTT-induced transcriptomic changes." (PMID 36552881, 2022).
Hyperglycemia (4 papers, 2013 to 2022). An increased concentration of glucose in the blood. "Hyperglycemia is known to cause elevated oxidative stress and both BACE1 and presenilin 1 expression are known to be stimulated by oxidative stress accompanied by an increase in Aβ production." (PMID 23894546, 2013). "This study evaluated the neuroprotective effects of piperine and expression of five candidate genes (BACE1, PSEN1, APAF1, CASPASE3, and CATALASE) in rat’s cerebral cortex induced hyperglycemia with STZ rat model." (PMID 33737876, 2020).
leukemia (4 papers, 2012 to 2024). A malignant (clonal) hematologic disorder, involving hematopoietic stem cells and characterized by the presence of primitive or atypical myeloid or lymphoid cells in the bone marrow and the blood. "For instance, specific PSEN1 knockout in hematopoietic progenitors demonstrated the importance of PSEN1/γ-secretase in developing and sustaining leukemia." (PMID 39360803, 2024). "Treatment with the PSEN1 inhibitor MRK-560 decreases the leukemia burden and increases the overall survival in T-ALL patient-derived xenografts in vivo, without causing gastrointestinal toxicity or decreasing the normal T-cell development." (PMID 33003595, 2020). "This is not the case for the selective PSEN1 inhibitor MRK-560, that demonstrated inhibition of mutant NOTCH1 processing and a decrease in the leukemia burden without causing gastrointestinal toxicity in T-ALL PDX in vivo." (PMID 33003595, 2020). "MRK-560 treatment decreases leukemia burden and increased OS with no associated gut toxicity in T-ALL patient-derived xenografts in vivo, suggesting that, similar to SERCA inhibition, disruption of PSEN-1 may preferentially affect mutated proteins." (PMID 33407740, 2021).
melanoma (4 papers, 2021 to 2023). A malignant, usually aggressive tumor composed of atypical, neoplastic melanocytes. "Interestingly, it has been demonstrated that the PSEN1 L166P and G384A mutations cause re-localization of γ-secretase in MNT-1 cells (highly pigmented human melanoma cells), which significantly promotes the generation of intracellular long Aβ4270." (PMID 37553376, 2023). "However, this appears in contrast with a more recent study that showed how advanced-stage/aggressive melanoma actually expresses low levels of presenilin-1 and that gamma-secretase inhibition in aggressive melanoma cells increased presenilin-1 levels and reduced melanoma cell migration." (PMID 36361539, 2022).
Senile plaques (4 papers, 2017 to 2023). Senile plaques are extracellular deposits of amyloid in the gray matter of the brain. "For patient EXT 149, who carried the c.518T>G, p.Leu173Trp de novo PSEN1 mutation, rare senile plaques associated with numerous cotton wool deposits and neurofibrillary tangles were present in hippocampal regions and cortical areas." (PMID 28350801, 2017). "We also demonstrated that early-life, time-limited (i.e., perinatal) SAM supplementation is as effective as prolonged supplementation to adult mice in modulating PSEN1 and reducing senile plaques." (PMID 37511434, 2023). "Moreover, trientine can significantly reduce the APP/presenilin-1 (PS1) mouse brain senile plaques and reduce copper and zinc accumulation in plaques." (PMID 34202166, 2021). "In APP/PS1 mice harbouring the mutant human β-amyloid precursor protein (APPswe) and mutant presenilin 1 (PS1ΔE9) an increase in the resting Ca2+ concentrations and Ca2+ hyperactivity with abnormal long-projecting intercellular Ca2+ waves were detected in astrocytes surrounding senile plaques." (PMID 28208745, 2017).
vascular dementia (4 papers, 2020 to 2025). A degenerative vascular disorder affecting the brain. "Among these variants, APP p.L364F and PSEN1 p.R54X were found in vascular dementia cases with AAO ranges of 56–60 years and 41–45 years, respectively." (PMID 40813364, 2025). "Among these variants, APP p.L364F and PSEN1 p.R54X were found in vascular dementia cases with AAO ranges of 41–45 years and 46–50 years, respectively." (PMID 39606324, 2024).
viral infection (4 papers, 2019 to 2025). "In addition since there is evidence that even the FAD patients who carry the PSEN1 mutation have signs of viral infection that affect the hippocampus through the olfactory bulb, which suggests treatments for MAD would have relevance also with EOAD." (PMID 39416952, 2024). "Lower cognitive performance was associated with CNVs in PSEN1 (exons 1, 9, 12), GRN (exons 1, 6, 12), and MAPT (exons 2, 8), along with viral infections (HSV-1, HSV-2, HAV-2)." (PMID 40725212, 2025). "Our studies here provide evidence to demonstrate coordination between NUP98 and NRG1-ERBB4/PSEN1 signaling proteins in the host response to viral infection and identify a previously unrecognized mechanism of enteroviral pathogenesis of viral myocarditis." (PMID 31396490, 2019). "Genetic analysis identified copy number variations (CNVs) in the APP, PSEN1, PSEN2, MAPT, and GRN genes, while viral infections (HSV-1, HSV-2, CMV, EBV, HIV, SARS-CoV-2, Hepatitis A, B, and C) and vitamin D, B12, and B9 deficiencies were measured." (PMID 40725212, 2025).
Acute encephalopathy (3 papers, 2020 to 2025). "In this study, using whole-exome sequencing, we discovered the first nonsense mutation in the PSEN1 gene in a family whose members presented with acute encephalopathy as the prominent symptom and simultaneously suffered from retinitis pigmentosa." (PMID 32431660, 2020). "In this study, all three family members with the PSEN1 mutation presented at a young age with acute encephalopathy as the prominent symptom, characterized by the acute onset of fever, impaired consciousness or mental abnormality, signs of pyramidal tract damage, and meningeal irritation." (PMID 32431660, 2020). "A novel PSEN1 gene mutation, chr14: 73673106 c.881G>A, may result in acute encephalopathy and may be a causative mutation for retinitis pigmentosa." (PMID 32431660, 2020).
Brain atrophy (3 papers, 2016 to 2024). Partial or complete wasting (loss) of brain tissue that was once present. "This is the first study to show that PSEN1 rare variants collectively show a significant association with the brain atrophy in regions preferentially affected by LOAD, providing further support for a role of PSEN1 in LOAD." (PMID 27535542, 2016).
colorectal cancer (3 papers, 2021 to 2024). A primary or metastatic malignant neoplasm that affects the colon or rectum. "Increased expression of PSEN1 in colorectal cancer is associated with enhanced tumor development through heightened EGFR signaling via NOTCH1 processing and activation of the COX-2-PGE2 pathway." (PMID 39267750, 2024). "Overexpression of PSEN1 promotes peritoneal metastasis in colorectal cancer, which is thought to be associated with E-cadherin proteolysis and nuclear translocation." (PMID 36117156, 2022).
familial disease (3 papers, 2015 to 2025). "By looking at the causes of FAD, genetic analyses have indicated that mutations in APP (amyloid precursor protein), PSEN-1 (presenilin 1) or PSEN-2 (presenilin 2) genes are the cause of the different types of familial disease." (PMID 25954151, 2015).